EGFR (epidermal growth factor receptor)
Diseases named in the same sentence as EGFR in open-access papers (continued):
Sharing a sentence is not in itself a finding about the gene and the disease.
cancer (continued). "Current therapeutic strategies for CRC are mainly limited to epidermal growth factor receptor (EGFR) monoclonal antibody-based treatment, which is focused on inhibiting the MAPK/ERK pathway (also called the EGFR-RAS-RAF-MEK-ERK pathway) and thus attenuates cancer cell proliferation." (PMID 32143717, 2020). "The mechanisms responsible for sorafenib resistance are complex, but includes the activation of epidermal growth factor receptor (EGFR), c-Jun and the Akt pathway, as well as increases in cancer stem cells, and enhancement of epithelial-mesenchymal transition (EMT)." (PMID 32631382, 2020). "Moreover, VEGFA, EGFR, CASP3, AKT1, and CCND1 were identified as hub genes in the antilung cancer of cinobufotalin injection." (PMID 32148531, 2020). "Further in vitro and in vivo experiments have identified many of the secreted signaling molecules (e.g., acetylcholine, nerve growth factor) that are passed between neurons and cancer cells, as well as the major signaling pathways (e.g., MAPK/EGFR) involved in these trophic interactions." (PMID 33322770, 2020). "However, the use of these EGFR-targeted therapies in the treatment of TNBC and other cancer types have led to dismal outcomes with rapid disease recurrence and metastasis." (PMID 32784650, 2020). "Alteration of the erythroblastic leukemia viral oncogene homolog (ErBb) family of the receptor tyrosine kinases (RTK) epidermal growth factor receptor (EGFR; also called ERBB1), ERBB2, ERBB3, and ERBB4 by comprehensive genomic or proteomic profiling has been identified in various cancer patients." (PMID 32708604, 2020). "Since several P2Y receptors have been shown to activate oncogenic EGFR signalling, we hypothesised that inhibition of P2Y12 may reduce epidermal growth factor receptor (EGFR) signalling and cancer growth." (PMID 31968611, 2020). "The mechanisms of Sora resistant are complex and undefined, but include increased epidermal growth factor receptor (EGFR) expression, c-Jun and Akt activation of HCC cells, epithelial-mesenchymal transition (EMT), increased cancer stem cells, and an increase in the hypoxic environment." (PMID 32000827, 2020). "Regulation of the ciRS-7/miR-7/EGFR axis is a crucial molecular mechanism in PTC, and this pathway may be a novel target for the diagnosis and therapy of this cancer." (PMID 32685551, 2020). "Therefore, therapeutic approaches using drugs that inhibit both EGFR and VEGFR2 can increase the efficiency of cancer therapy and overcome the resistance problem." (PMID 33096664, 2020). "Moreover, dual targeting of endothelial and cancer cells, using nanobody–photosensitizer conjugates targeting VEGFR2 and EGFR, respectively, showed improved efficacy." (PMID 32977602, 2020). "Intriguingly, EMT and immune checkpoint proteins maybe related to each other as EGFR activation induces EMT and PDL1 expression in cancer." (PMID 32927768, 2020). "Our study differs from Garofalo, placing miR-221 up-stream of EGFR rather than being contingent upon it and this is most likely due to differences in cancer type and cell line." (PMID 33082482, 2020). "For GI cancer, EGFR, PDGFRA, VEGFA, PDPK1, and MCL1, etc. could be validated as drug targets for anti-cancer drugs." (PMID 32523951, 2020). "EGFR is frequently over-activated in cancer and studies have shown that it is not expressed by normal Schwann cells but it is overexpressed in subpopulations of NF1 mutant Schwann cells." (PMID 32858845, 2020).
cancer (continued). "Previous studies have shown that combining aspirin with erlotinib enhanced the effects of erlotinib in killing EGFR‐mutant NSCLC cells and that combining aspirin with sorafenib and other drugs significantly suppressed cancer growth and prolonged remission in xenograft models." (PMID 32239624, 2020). "The results showed that the five anti-EGFR sdAbs specifically bound to the human cancer cells A549, MCF-7 and DU145 and not the cells 293T and 3T3 as negative controls." (PMID 33023595, 2020). "Then, we investigated the effect of both non-conjugated and EGF-TiO2 PEG NPs on cancer cell line proliferation and growth via the investigation of EGFR localization and expression." (PMID 33003324, 2020). "Activating KRAS mutations and PTEN loss reportedly lead to PI3K/AKT pathway activation, independent of EGFR tyrosine kinase status, driving the downstream cancer survival pathways and supporting resistance." (PMID 32296588, 2020). "These properties make BC a very efficient anti-EGFR treatment which significantly reduces EGFR in cancer cells whilst having no significant impact (regarding EGFR levels) on normal cells." (PMID 32401801, 2020). "The MAPK inhibitor and EGFR inhibitor also blocked COM D24-induced cancer cell invasion from the spheroids but not as efficiently as the Akt inhibitor." (PMID 32731484, 2020). "Hence, combination treatment consisting of EGFR, cMET, and PARP1 inhibitors posits a novel therapeutic strategy in cancer treatment involving overexpression of PARP1/EGFR/cMET, which are frequent alterations in most solid tumors." (PMID 32295316, 2020). "In particular, PGE2 and EGF/EGFR may cooperate to promote growth, invasion, epithelial mesenchymal transition (EMT), and a stem-like phenotype of cancer cells." (PMID 33271839, 2020). "It is a target of CD148, but the regulation of EGFR by CD148 has not been studied in certain cancers." (PMID 32201537, 2020). "In addition to the canonical activation of EP receptors, PGE2 has been shown to promote cancer progression through the interaction with oncogenic signals, including epidermal growth factor (EGF) and its receptor (EGFR)." (PMID 33271839, 2020). "In addition to clarifying the role of Syk in EGFR signalling and the prognosis of patients with SCC, we tested the combined effects of Syk and PARP inhibition on cancer cell death." (PMID 32093123, 2020). "Considering that high-dose VitC is known to be safe in cancer patients, our findings might have clinical impact on CRC patients treated with anti-EGFR therapies." (PMID 32183295, 2020). "EGFR is a transmembrane protein that is activated by EGF ligands, which are leading to the stimulation of AKT and ERK signaling pathways controlling mainly migration, invasion, anoikis resistance, and stem cell-like properties during cancer progression." (PMID 32376896, 2020). "Overexpression of receptors such as EGFR, transforming growth factor beta (TGFβ) receptor, c-met, and tropomyosin receptor kinase B (TrkB), and growth factors such as EGF, TGF, HGF, and BDNF have been found to drive aggressive and resistant cancer phenotypes." (PMID 33158043, 2020). "Several possible mechanisms of sorafenib resistance have been proposed, including epidermal growth factor receptor (EGFR) activation, Akt activation, c-Jun activation, induction of hypoxia, autophagy, apoptosis, cancer stem cell renewal, and epithelial–mesenchymal transition activation." (PMID 32203105, 2020). "Our own work also showed that ensemble-based docking is required to explain the preference of gatekeeper mutant EGFR (epidermal growth factor receptor) binding with gefitinib, a targeted anti-cancer drug, rather than ATP." (PMID 33178418, 2020).
cancer (continued). "Additionally, HPV elevates COX-2 levels through the EGFR pathway and HIV promotes elevated COX-2 levels in cervical tissue as well as increases PGE2 levels eliciting inflammation and progression of cancer." (PMID 32982722, 2020). "It likewise provides insights into the mechanism of EGFr TKI‐induced diarrhea, and could be relevant in designing strategies to overcome important side effects of EGFr TKIs during cancer treatment." (PMID 32652816, 2020). "Furthermore, EGFR and HER2 localization in lipid rafts is discussed to play a role in cancer cell drug resistance, e.g., regarding treatment with trastuzumab or tyrosine kinase inhibitors." (PMID 32660617, 2020). "The knockdown of LINC00152 has been reported to decrease EGFR expression, which indicates that LINC00152 might regulate cancer progression via the EGFR pathway." (PMID 32774169, 2020). "In various cancers, curcumin has been shown to inhibit growth and proliferation of cancer cells by targeting various survival pathways, including JAK/STAT3, PI3-kinase/AKT, Transforming growth factor beta (TGF-β), Epidermal Growth Factor Receptor (EFGR), and NF-кB." (PMID 31936675, 2020). "Furthermore, on TKI-sensitive cell lines, EGFR inhibition significantly reduced CD47 expression on the surface of preapoptotic cells, favoring more efficient engulfment of cancer cells by monocyte-derived dendritic cells." (PMID 33015199, 2020). "This study found that HSC-3 squamous carcinoma cell EVs containing EGFR could increase vimentin protein levels and induce a spindle shape morphology while decreasing E-cadherin levels in recipient RT7 cancer cells." (PMID 33143170, 2020). "Therefore, EGFR signaling leads to ILF3 stabilization, promotes the mRNA stability of SGOC genes, and furthers serine biogenesis in cancer." (PMID 31772275, 2020). "In addition, a list of known JUN-target genes, including MMP3, CD44, EGFR, ENPP246, and MGST147, were markedly upregulated in cancer cells with SH3RF3 overexpression." (PMID 32427938, 2020). "Akt-silenced cancer cells were not stimulated to migrate and invade by fibroblast-CM and did not survive the addition of an EGFR inhibitor." (PMID 32731484, 2020). "Although ERK1/2, EGFR, or even DDR1 are known as targets to interfere with cancer development and malignancy in oncology for many years, the combined inhibition of these targets offers a novel treatment option in a synergistic manner, especially relevant for TNBC cells." (PMID 32668815, 2020). "Interestingly, PCZ was shown to inhibit dynamin-dependent endocytosis of membrane proteins such as EGFR, PD-L1 or HER2 which are the targets of therapeutic antibodies in several cancers." (PMID 33240808, 2020). "Finally, in the 21 plasma samples collected from advanced-stage patients who developed drug resistance to first-line EGFR-TKIs, Sel-Cap detected three times more T790M-positive plasma samples than a different NGS-based cancer panel." (PMID 33266057, 2020). "Furthermore, we demonstrate that the SWIR fluorescence imaging using ICG–antibody conjugates is useful for the elucidation of the expression level of cancer-specific membrane proteins such as HER2, EGFR, VEGFR-2, and PD-L1 in vivo." (PMID 35519107, 2020). "We focused on biomarkers that exhibit the various hallmarks of cancer, and for which NIRF probes are already clinically available: epidermal growth factor receptor (EGFR), vascular endothelial growth factor-A (VEGF-A), integrin αvβ6 and epithelial cell adhesion molecule (EpCAM)." (PMID 32545676, 2020). "More significantly, studies have shown that EGFR is dysregulated in many solid tumors, and PI3K-AKT signaling can be used as a downstream regulatory pathway for EGFR to mediate the occurrence and progression of disease, as confirmed in many cancers." (PMID 32536817, 2020). "Stratification of prexasertib clinical data based on EGFR expression status could offer new insight into the clinical use of prexasertib as a monotherapy for TNBC and other cancers." (PMID 35582228, 2020).
cancer (continued). "These suggested that GALNT7 promoted cancer development by activating the JAK-ATAT or CAMs signaling pathway.Earlier studies also showed that EGF was involved in cell proliferation through activating the EGF receptor (EGFR) signaling pathway." (PMID 32308562, 2020). "IL-13/IL13Rα2 activation of PTP1B was independent of EGFR activation and was critical for migration and invasion of cancer cells." (PMID 32098194, 2020). "The epidermal growth factor receptor (EGFR) and its ligands are involved in cancer pathogenesis and they might serve as circulating biomarkers." (PMID 32317675, 2020). "The WM73 module evidently suggested participation in the Hippo signalling pathway that might interact with the ERBB/EGFR signalling pathway, forming a positive feed‐forward loop to drive cancer development and progression." (PMID 32616892, 2020). "Expression of PD-L1 is induced via oncogenic signaling pathways, such as RAS/RAF/MEK/mitogen-activated protein kinase-ERK, phosphatidylinositol-3 kinase/phosphatase and tensin homolog/Akt/mammalian target of rapamycin, EGFR, and EML4-ALK pathways, in many cancer types." (PMID 33324391, 2020). "Moreover, OPN can directly interact with various membrane receptors, including EGFR, CD44, VEGF and integrins, thereby promoting cancer metastasis." (PMID 32862200, 2020). "Binding of EGFR with its ligands TGFα or EGF results in autophosphorylation of RTK followed by activation of downstream pathways, including the RAS pathway, that regulate cell proliferation and differentiation in various types of cancer." (PMID 32432044, 2020). "In EGFR-TKI-resistant cancers, EGFR-TKI and FGFR-TKI combination treatment is no more beneficial for inhibiting cell growth than FGFR-TKIs alone." (PMID 33092268, 2020). "In lung, mCRC and HNSCC cancer patients, despite the good tolerability, combination therapy of dasatinib with EGFR inhibitors leads to no consistent clinical responses." (PMID 32517369, 2020). "In addition, the interactions among GRB2, EGFR, HIF1A, and SLC2A1 were also highly correlated with cancer in the KEGG “Pathways in cancer” (pathway #5200)." (PMID 32170141, 2020). "Moreover, several other cancer-related proteins (NRAS, Src, c-Met, c-Kit, EGFR, MCAM, annexin A1, HAPLN1, LGALS1, GALS3, NT5E, and PMEL) were detected in MTEX originating from various melanoma cell lines." (PMID 32709086, 2020). "Despite the rapid advances in cancer therapies such as immunotherapy or molecular therapies targeting the epidermal growth factor receptor, the overall survival of SCLC has not significantly improved 27,28." (PMID 32292508, 2020). "The stage‐dependent pathway analyses (of phase 3) suggest that the functional signals were mostly related to cell‐to‐cell communication (e.g., Endocytosis) and cancer dormancy (e.g., TGF‐beta signaling) in early‐stage LC and cell proliferation in advanced LC stage (e.g. EGFR)." (PMID 31851411, 2020). "Previous data showed that only a minority of cancer cells harboured known genetic resistance drivers when clinical resistance to single-agent EGFR-Abs had evolved, supporting the activity of non-genetic resistance mechanisms." (PMID 33322618, 2020). "Recent reports have suggested that inhibitors of the epidermal growth factor receptor (EGFR), a receptor tyrosine kinase (RTK), may have analgesic effects in cancer patients suffering from neuropathic pain." (PMID 32111605, 2020). "Interestingly, the downregulation of AIMP2-DX2 expression by shRNA suppressed the epidermal growth factor receptor (EGFR)/MAPK signaling pathway, thereby inhibiting glucose uptake and cancer cell growth." (PMID 32709848, 2020). "Cetuximab is widely used to treat HNSCC, yet therapy is not individualised based on EGFR expression, unlike for EGFR inhibitors in other cancers, since EGFR copy number does not act as a predictive biomarker for the efficacy of cetuximab in HNSCC." (PMID 33322840, 2020).
cancer (continued). "In any case, in different types of cancer cells, the levels of GOLPH3 could affect the glycosylation of EGFR in different ways, and this could result also in different outcomes." (PMID 33238647, 2020). "However, the role of the crosstalk between EGFR and the PAF-PAFR axis in other types of cancer has yet to be investigated." (PMID 33392068, 2020). "Indeed, there have been clinical trials utilizing EGFR and HER2 amplification in these two cancer types." (PMID 31942259, 2020). "iEFs inhibit EGFR phosphorylation in EGF-treated cancer cells thereby altering actin cytoskeleton structure and critical processes involved in cell motility—a potential mechanism explaining the observed hindrance of cancer cell motility by iEFs." (PMID 31428691, 2019). "The effects on transcription following activation of EGFR have been studied in several cancer and non-cancer cell types and with the use of different methodologies." (PMID 30736768, 2019). "Targeted therapy aims to block signaling processes that sustain the proliferation or survival of the cancer cells, but for CRC, targeted therapy has so far narrowly focused on blocking the function of EGFR or angiogenesis, mostly using monoclonal antibodies against EGFR or VEGFR." (PMID 30754629, 2019). "In order to further confirm whether compound 15c can impede the phosphorylation of EGFR and FGFR1 in cells, the kinase inhibitory activity of 15c was detected in various ligand stimulated cancer cells." (PMID 31998131, 2019). "In cancer, the altered EGFR is always on, which allows the cell to rapidly grow without any control, resulting in cancer." (PMID 31741433, 2019). "Both EGFR and CXCR7 inhibition showed synergetic suppression of cancer cell growth." (PMID 30935067, 2019). "Since human tumors of epithelial origin often display elevated EGFR (epidermal growth factor receptor) expression, they used EGFR as a receptor target in the cancer drug delivery system and GE11 peptide as an alternative to the ligand EGF with its strongly mitogenic and neoangiogenic character." (PMID 30901915, 2019). "EGFR-TKIs have been also shown to activate autophagy in NSCLC and other cancer cells." (PMID 31196210, 2019). "Emerging evidence has revealed that miRNAs are related to several aspects of cancer pathogenesis, including self-renewal, invasion, and metastasis, by targeting cyclin-dependent kinase 6 (CDK6), epidermal growth factor receptor (EGFR), MAPK, and PI3K/AKT signaling pathways." (PMID 30530570, 2019). "In this study, we examined the HER2/c-erbB-2, EGFR expression in cancer and normal gastric tissue of 67 patients with gastric carcinomaby immunohistochemistry assay and explored the correlation between HER2/c-erbB-2, EGFR expression and clinicopathological features and prognosis." (PMID 33817143, 2019). "This study may provide new insight into mechanisms of acquired resistance to EGFR TKI in NSCLC and a potential target for ant-cancer drug treatment." (PMID 31762810, 2019). "It is worth noting that the majority of EGFR positive cancers do not respond to current anti-EGFR agents." (PMID 31508364, 2019). "Epidermal growth factor receptor (EGFR) plays an integral role in the tumorigenic process, which makes it an attractive target for pharmacologic inhibition by the induction of autophagic cancer cell death." (PMID 31014370, 2019). "To date, three anti-EGFR mAbs, cetuximab (Erbitux®, Bristol-Myers Squibb/Merck KGaA), panitumumab (ABX-EGF/ Vectibix®, Amgen), and necitumumab (Portrazza®, Eli Lilly and Company, USA), are currently in widespread use in cancer treatment, most notably for CRC." (PMID 30975211, 2019). "Overall EGFR expression and distribution was not markedly different between these different cancer cells, and EGFR was largely localized to the plasma membrane." (PMID 30890751, 2019). "We showed that DYRK1A repression could enhance the anti‐cancer effect of AZD9291 by inducing apoptosis and suppressing cell proliferation in EGFR wild‐type NSCLC cells." (PMID 31454149, 2019).